TUG1 (taurine up-regulated 1)
Diseases named in the same sentence as TUG1 in open-access papers (continued):
Sharing a sentence is not in itself a finding about the gene and the disease.
non-small cell lung carcinoma (33 papers, 2014 to 2024). A group of at least three distinct histological types of lung cancer, including non-small cell squamous cell carcinoma, adenocarcinoma, and large cell carcinoma. "We examined the expressions of TUG1 in a cohort of 89 patients with non-small cell lung cancer (NSCLC) to determine the association between TUG1 expression and clinical parameters." (PMID 27485439, 2016). "Although most of these works presented TUG1 as having an oncogenetic role, it is downregulated and associated with better survival in glioblastoma and non-small cell lung cancer, and TUG1 may function as a tumor suppressor in these cancer cell models." (PMID 29657297, 2017). "In a clinical study involving 89 patients with non-small cell lung cancer, the expression of the lncRNA taurine-upregulated gene 1 (TUG1) was determined to be significantly downregulated." (PMID 38473229, 2024). "The expression of upregulated lncRNA TUG1 has been shown to promote the proliferation of esophageal squamous cells and plays a role in promoting the proliferation of non-small-cell lung carcinoma." (PMID 36901763, 2023). "TUG-1 is aberrantly expressed in cancer and has been involved in the progression of various types of tumors: hepatocellular carcinoma, non-small-cell lung cancer (NSCLC), cancer of the bladder, and cancer of the colon." (PMID 35132340, 2022). "It was found that compared with normal lung tissues/cells and paracancerous tissues, the expression of TUG1 in non-small-cell lung cancer tissues or cells was significantly reduced." (PMID 34660799, 2021). "Recent findings have proven its association with various cancers; dysregulated expression level of TUG1 was described in colorectal cancer, gastric cancer, non-small cell lung cancer (NSCLC), hepatocellular cancer, and BC." (PMID 32756406, 2020). "The pooled HR suggested that high TUG1 expression correlated with poor OS (pooled HR=1.41, 95% CI: 1.01-1.98) in cancer types other than non-small cell lung cancer." (PMID 28977959, 2017). "But in another study, knockdown of TUG1 promoted tumor cell proliferation in non-small cell lung carcinoma via regulation of the expression of homeobox B7 (HOXB7)." (PMID 26078353, 2015). "A previous study showed that TUG1 was downregulated in non-small cell lung cancer." (PMID 35982898, 2022). "The expression of lncRNA TUG1 was down-regulated in non-small cell lung cancer." (PMID 34039257, 2021). "lncRNA TUG1 inhibited proliferation of non-small cell lung cancer." (PMID 34039257, 2021). "lncRNA TUG1 inhibited the proliferation of non-small cell lung cancer cells." (PMID 34039257, 2021). "Conversely, TUG1 is generally downregulated in non-small-cell lung carcinoma (NSCLC) tissues." (PMID 30595764, 2018). "However, TUG1 has been shown to act as a tumor suppressor in non-small cell lung cancer, where TUG1 knockdown promoted tumor cell proliferation through epigenetic regulation of HOXB7 expression." (PMID 29371936, 2017). "Our previous study showed that TUG1 could affect cell proliferation through epigenetically regulating HOXB7 in human non-small cell lung cancer." (PMID 26913601, 2016). "However, the expression of lncRNA TUG1 was down-regulated in non-small cell lung cancer." (PMID 34039257, 2021). "Here we report that taurine-upregulated gene 1 (TUG1), a 7.1-kb lncRNA, recruiting and binding to polycomb repressive complex 2 (PRC2), is generally downregulated in non-small cell lung carcinoma (NSCLC) tissues." (PMID 24853421, 2014). "For instance, TUG1 could regulate the expression of HOXB7 by binding to PRC2, then affects cell proliferation in human non-small cell lung cancer." (PMID 28069000, 2017).
non-small cell lung carcinoma (continued). "Taurine Up-regulated Gene 1 (TUG1), a 7.1-kb lncRNA, recruiting and binding to polycomb repressive complex 2 (PRC2), is found to be disregulated in non-small cell lung carcinoma (NSCLC) and esophageal squamous cell carcinoma (ESCC)." (PMID 26336870, 2015).
Sepsis (33 papers, 2020 to 2025). Sepsis is defined as life-threatening organ dysfunction caused by a dysregulated host response to infection. "For instance, lncRNA TUG1 is involved in sepsis-associated AKI by influencing cytokines production and autophagy, thus promoting cell proliferation and inhibiting cell apoptosis." (PMID 33663500, 2021). "The current study suggested that TUG1 was downregulated in sepsis and that its upregulation contributes to improved protection against the sepsis-caused inflammatory damage by impairing miR-9-5p-targeted inhibition of SIRT1." (PMID 34743197, 2021). "Cumulatively, TUG1 ameliorates sepsis-associated inflammation and apoptosis through miR-34b-5p/GAB1 axis." (PMID 34956235, 2021). "Up-regulation of TUG1 in these animals could ameliorate sepsis-associated lung injury, apoptosis and inflammatory reactions." (PMID 34956235, 2021). "TUG1 was discovered to play protective roles in the progression of sepsis-associated AKI, while a recent research showed silencing TUG1 could attenuate inflammation and apoptosis in renal ischemia-reperfusion injury model." (PMID 34630395, 2021). "Additionally, in lung injury mediated by sepsis, lncRNA taurine up-regulated 1 (TUG1) guards against sepsis-caused ALI through the regulation of the miR-34b-5p/GRB2-associated binding protein 1 (GAB1) axis." (PMID 34592882, 2021). "Also, it was reported that TUG1 is able to affect the development of sepsis-associated acute kidney injury via modulating NF-κB pathway." (PMID 32471511, 2020). "For example, EV’s resealed by endothelial progenitor cells promote M2 macrophage polarization by suppressing miR-9-5p on SIRT1 through the transfer on lncRNA taurine upregulated gene 1 (TUG1), an important lncRNA that is downregulated during sepsis." (PMID 38260141, 2023). "It has also been recognized that circANKR inhibits the NF-κB signaling pathway by acting on the miR-31/MyD88 axis, and lncRNA TUG1 also alleviates sepsis-induced acute lung injury by targeting miRNA-34b-5p." (PMID 36526959, 2022). "TUG1 expression was markedly downregulated in lung tissue and airway epithelial cells in sepsis-induced-ALI animals." (PMID 36354526, 2022). "In light of the preceding evidence, we set out to investigate the TUG1-mediated anti-inflammatory mechanism in the sepsis models." (PMID 34743197, 2021). "Essentially, our in vivo murine model validated the protective role of TUG1 against sepsis-evoked liver damage." (PMID 34743197, 2021). "The effect of EPC-derived EVs carrying TUG1 on multiple organ damage in sepsis was further investigated in vivo." (PMID 34743197, 2021). "In one previous study, five lncRNAs, including FENDRR, MALAT1, TUG1, CRNDE, and ANCR, were associated with sepsis." (PMID 34483898, 2021). "NEAT1, MALAT1, THRIL, XIST, MIAT and TUG1 are among lncRNAs that participate in the pathoetiology of sepsis-related complications." (PMID 34956235, 2021). "Long noncoding RNAs (lncRNAs) Colorectal Neoplasia Differentially Expressed (CRNDE) and taurine-upregulated gene 1 (TUG1) play similar roles in sepsis, indicating the existence of the crosstalk between them." (PMID 34872438, 2021). "Several researchers have demonstrated the downregulation of TUG1 in sepsis and its potential as an inhibitor of sepsis-induced inflammation and acute kidney injury." (PMID 34743197, 2021). "Another study has demonstrated down-regulation of TUG1 while up-regulation of miR-223 in the plasma samples of sepsis patients." (PMID 34956235, 2021). "While MALAT1 and NEAT1 promoted sepsis-induced inflammation in organ injury, TUG1 exhibited protective effects by inhibiting apoptosis, promoting cell proliferation, and downregulating immune response in sepsis." (PMID 34630395, 2021). "Our study additionally substantiated the protective role of EPC EVs encapsuled TUG1 against sepsis in the murine model." (PMID 34743197, 2021).
Sepsis (continued). "This study was therefore carried out to analyze the potential crosstalk between CRNDE and TUG1 in sepsis, with a focus on sepsis-induced cell apoptosis in heart." (PMID 34872438, 2021). "Significantly, Cheng and his colleagues recently found five lncRNAs (FENDRR, MALAT1, TUG1, CRNDE, and ANCR) were correlated with sepsis-associated mRNA modules perhaps by acting as competing endogenous RNAs (ceRNAs)." (PMID 34483898, 2021). "We observed the expression patterns of CRNDE and TUG1 in sepsis patients and their similar roles in the regulation of LPS-induced apoptosis of cardiomyocytes, suggesting possible crosstalk between them." (PMID 34872438, 2021). "Correlations between CRNDE and TUG1 across plasma samples from both sepsis and control samples were then analyzed." (PMID 34872438, 2021). "Based on these results, TUG1 has been suggested as a biomarker for prediction of course and prognosis of sepsis." (PMID 34956235, 2021). "In ALI, taurine up-regulated 1 was identified to alleviate sepsis-induced inflammation and apoptosis via the miR-34b-5p/ growth factor receptor bound protein 2-associated protein 1 axis." (PMID 34261477, 2021). "The results showed that CRNDE and TUG1 were positively and significantly correlated across sepsis samples." (PMID 34872438, 2021). "TUG1 was underexpressed in CLP-induced sepsis, and its reexpression induced anti-inflammatory macrophage polarization and suppressed macrophage-medicated inflammatory injury to the pulmonary vascular endothelium." (PMID 34743197, 2021). "In conclusion, CRNDE and TUG1 are downregulated in sepsis and they positively regulate each other to suppress the apoptosis of cardiomyocytes." (PMID 34872438, 2021). "Previous studies have shown that both lncRNAs Colorectal Neoplasia Differentially Expressed (CRNDE) and taurine-upregulated gene 1 (TUG1) play protective roles in sepsis-induced kidney injury." (PMID 34872438, 2021). "Meanwhile, an increasing number of studies have shown that lncRNAs, such as HOTAIR and TUG1, have protective effects in the regulation of sepsis-induced AKI." (PMID 34630395, 2021). "It was observed that TUG1 was downregulated in sepsis and overexpression of TUG1 targets the axis of miR-142-3p/sirtuin 1 and regulates the NF-kB pathway to suppress disease progression." (PMID 34872438, 2021). "The induction of TUG1 ameliorated sepsis-induced lung injury, the secretion proinflammatory cytokines, and apoptosis via inhibiting miR-34b-5p and promoting GAB1." (PMID 32087725, 2020). "The overexpression of TUG1 in ALI mice ameliorated sepsis-induced pulmonary injury, apoptosis and inflammation." (PMID 32087725, 2020). "To further ascertain the beneficial effect of TUG1 overexpression on sepsis-induced lung damage, we established an in vitro PMVECs cell model of to mimic in vivo septic epithelium via LPS stimulation." (PMID 32087725, 2020). "In the present study, we reported that lncRNA TUG1 ameliorated sepsis-induced ALI by the suppression of inflammatory responses and apoptotic activity, via targeting miR-34b-5p and GAB1." (PMID 32087725, 2020). "To further explore the mechanisms of TUG1/miR-34b-5p-mediated regulation in sepsis-induced ALI, we used TargetScan database to predict a downstream target of miR-34b-5p." (PMID 32087725, 2020). "In this study, we aimed to investigate the expression and regulation role of TUG1 in sepsis-induced ALI using a murine septic model and an in vitro cell culture model induced by lipopolysaccharide (LPS) stimulation." (PMID 32087725, 2020). "Further, it was found that lncRNA taurine upregulated gene 1 (TUG1) in EPC-EVs upregulated sirtuin 1 (SIRT1) to facilitate the polarization of M2 macrophages by competitively binding to miR-9-5p thereby ameliorating sepsis." (PMID 38840175, 2024).
Sepsis (continued). "Taurine upregulated gene 1, or TUG1, is another lncRNA that shows an association with diabetic kidney diseases and can be correlated to disease-specific damage in the kidney due to sepsis and ischemia/reperfusion (I/R) stress." (PMID 40176927, 2024). "Moreover, ginsenoside Rg3 can alleviate sepsis-related hepatic injury through modulation of TUG1/miR-200c-3p/SIRT1 axis." (PMID 37441551, 2023). "Furthermore, EPC-derived EVs promote macrophage M2 polarization to alleviate sepsis by delivering the lncRNA TUG1." (PMID 36579343, 2022). "In a cell model of sepsis, TUG1 up-regulation could present human umbilical vein endothelial cells from LPS-induced apoptosis." (PMID 36163177, 2022). "EVs-specific TUG1 is also protective against sepsis-induced ALI." (PMID 36354526, 2022). "TUG1 alleviates sepsis-induced acute lung injury by targeting miR-34b-5p/GAB1." (PMID 34362467, 2021). "Although we failed to explore the in vivo crosstalk between them, we showed that CRNDE and TUG1 were positively correlated across plasma samples from both sepsis patients and healthy controls, suggesting the existence of the positive feedback loop in both sepsis patients and healthy controls." (PMID 34872438, 2021). "TUG1 reduces sepsis-induced pulmonary injury, apoptosis and inflammation in ALI." (PMID 34956235, 2021). "We found that both CRNDE and TUG1 were downregulated in sepsis." (PMID 34872438, 2021). "Additionally, CASC9 and TUG1 alleviated the sepsis-induced ALI via affecting the miR-195-5p/PDK4 axis and miR-34b-5p/GAB1 axis." (PMID 34126975, 2021). "This study mainly investigated the crosstalk between CRNDE and TUG1 in sepsis." (PMID 34872438, 2021). "Taurine upregulated gene 1 (TUG1) is a long noncoding RNA (lncRNA) that is downregulated in sepsis." (PMID 34743197, 2021). "We showed that TUG1 could also play protective roles in LPS-induced apoptosis of cardiomyocytes, suggesting that TUG1 may participate in multiple sepsis-induced organ failures." (PMID 34872438, 2021). "Consistently, our study also reported the downregulation of TUG1 in sepsis." (PMID 34872438, 2021). "We found that TUG1 exerted an anti-inflammatory function in sepsis." (PMID 34743197, 2021). "TUG1 has also been proven to be a critical player in sepsis-induced kidney injury." (PMID 34872438, 2021). "We found that both CRNDE and TUG1 were downregulated in sepsis and they could form a positive feedback loop to suppress the apoptosis of cardiomyocytes induced by LPS." (PMID 34872438, 2021). "Furthermore, a recent study found that diosmetin also has renoprotective effects in the sepsis-induced AKI model by activating the TUG1/Nrf2/HO-1 pathway." (PMID 34545331, 2021). "In conclusion, both CRNDE and TUG1 are downregulated in sepsis and they may form a positive feedback loop to suppress the apoptosis of cardiomyocytes induced by LPS." (PMID 34872438, 2021). "In summary, EPCs derived EVs transmit TUG1 to attenuate sepsis via macrophage M2 polarization." (PMID 34743197, 2021). "Finally, EPCs derived EVs carrying TUG1 were verified to ameliorate sepsis-induced organ damage in the murine model." (PMID 34743197, 2021). "Our study highlighted the therapeutic potential of TUG1 for the management of sepsis-induced ALI." (PMID 32087725, 2020). "Finally, to ascertain TUG1 alleviated sepsis-induced ALI via targeting miR-34b-5pand GAB1, we co-transfected PMVECs with TUG1-expressing vector and miR-34b-5p mimics (or control mimics) before LPS stimulation." (PMID 32087725, 2020). "TUG1 alleviated sepsis-induced inflammation and apoptosis via targeting miR-34b-5p and GAB1." (PMID 32087725, 2020). "Therefore, it is possible that CRNDE and TUG1 may interact with each other to participate in sepsis." (PMID 34872438, 2021). "Sepsis AKI may be relieved by upregulation of TUG1 through miR-142-3p/SIRT1 axis." (PMID 33663500, 2021). "Hence, EVs encapsuled TUG1 presents a potential strategy for the clinical treatment of sepsis." (PMID 34743197, 2021).
Sepsis (continued). "Hence, we explored whether miR-9-5p and SIRT1 participate in the protective role of EVs shuttled TUG1 in sepsis." (PMID 34743197, 2021). "Moreover, lncRNA TUG1 was downregulated in sepsis and might sponge miR-27a to downregulate expression of TNF-α, thereby inhibiting apoptosis of LPS-induced AC16 cells." (PMID 34055659, 2021). "Similarly, TUG1 was also significantly downregulated in the sepsis group (p < 0.001)." (PMID 34872438, 2021). "Therefore, lncRNA TUG1 may be used as a potential therapeutic target for sepsis-induced ALI." (PMID 36429069, 2022). "Therefore, CRNDE and TUG1 may postively regulate each other to inhibit cell apoptosis in sepsis." (PMID 34872438, 2021). "The current study was designed to explore the role of EPCs derived EVs transmitting TUG1 in macrophage polarization and macrophage-mediated inflammation in a cecal ligation and puncture (CLP)-induced sepsis mouse model." (PMID 34743197, 2021). "They identified five sepsis-related lncRNAs, including FENDRR, MALAT1, TUG1, CRNDE, and ANCR, whose functions were highly related with biological processes of sepsis." (PMID 34055659, 2021). "To conclude, the current study gives evidence for the contribution of TUG1 to macrophage polarization and its anti-inflammatory potency by blocking miR-9-5p-induced silencing of SIRT1 in sepsis." (PMID 34743197, 2021). "A previous study indicated the ability of TUG1 to impair miR-34b-5p-mediated down-regulation of GAB1, thereby exercising a preventive effect against sepsis-induced acute kidney injury." (PMID 34743197, 2021). "At present, studies of lncRNA expression in sepsis mainly focus on HOTAIR, MALAT1, NEAT1, TUG1, and UCA1." (PMID 34514170, 2021). "Among those lncRNAs, TUG1 is reported to principally impair miR-34b-5p-mediated downregulation of GAB1, thereby restraining sepsis-triggered acute kidney injury." (PMID 34743197, 2021). "Five lncRNAs, FENDRR, MALAT1, TUG1, CRNDE, and ANCR, were detected as sepsis regulators based on the interactions among lncRNAs and the identified coexpression modules." (PMID 32471511, 2020). "We identified five sepsis lncRNAs, FENDRR, MALAT1, TUG1, CRNDE, and ANCR, all of which connect five or more sepsis modules, indicating their functions are highly related with biological processes of sepsis." (PMID 32471511, 2020). "However, it remains unclear whether TUG1 has a regulatory role in sepsis-induced ALI." (PMID 32087725, 2020). "This study was then performed to explore the potential crosstalk between TUG1 and CRNDE in sepsis." (PMID 34872438, 2021). "Only MALAT1 and TUG1 were detected (RPKM > 0.2 in at least two samples of one group) in the RNA-seq data, and their expression levels were significantly different between no_sepsis and sepsis samples." (PMID 34483898, 2021). "who observed the overexpression of TUG1 could decrease TNF-α expression level and reduce sepsis-induced apoptosis of cardiomyocytes via ing miR-27a, which had a protective effect against sepsis-induced myocardial injury." (PMID 34630395, 2021). "Although most of the lncRNAs regulate none or merely a single sepsis module, FENDRR, MALAT1, TUG1, CRNDE, and ANCR connect multiple sepsis modules with the connectivity of 14, 10, 10, 8, and 5, respectively, which are expected to have high potentials to be involved in the sepsis progress." (PMID 32471511, 2020). "Five sepsis lncRNAs were ultimately identified, FENDRR, MALAT1, TUG1, CRNDE, and ANCR." (PMID 32471511, 2020). "Moreover, in vitro data showed that the production of GAB1 was inversely regulated by miR-34b-5p, but was positively correlated with the expression of TUG1, suggesting the involvement of GAB1 in sepsis-induced ALI." (PMID 32087725, 2020). "In another study, EVs from endothelial progenitor cells encapsulated TUG1 to stimulate M2 macrophage polarization and inhibited inflammation by suppressing miR-9-5p to upregulate SIRT1 expression, which prevented the development of sepsis and alleviated sepsis-induced renal damage." (PMID 40332144, 2025).